MUC2 (mucin 2, oligomeric mucus/gel-forming)
Diseases named in the same sentence as MUC2 in open-access papers (continued):
Sharing a sentence is not in itself a finding about the gene and the disease.
colorectal polyps (2 papers, 2010 to 2017). "Negative staining for MUC2 was shown in the binary logistic regression model to be valuable in predicting the risk of mucosal and muscularis mucosae invasion in colorectal polyps." (PMID 20929551, 2010). "Binary logistic regression analysis indicated that positive staining for MUC1, and MUC6, and negative staining for MUC2 would increase the risk of invasion to mucosa or the muscularis mucosae in colorectal polyps." (PMID 20929551, 2010). "MUC1, MUC2, MUC5AC, and MUC6 have the potential to be used as predictors of malignant transformation and invasion to mucosa or the muscularis mucosae in colorectal polyps." (PMID 20929551, 2010). "The aim of the present study was to determine the pattern of expression of MUC1, MUC2, MUC5AC and MUC6 in colorectal polyps and to evaluate the applicability of using mucin expression in predicting the extent of malignant transformation in colorectal polyps." (PMID 20929551, 2010).
ductal breast carcinoma (2 papers, 2014 to 2020). "In breast ductal adenocarcinomas, MUC2 and MUC5AC are localized in cytoplasm with granular staining pattern, whereas distribution of MUC5B expression changes from apical localization in non-malignant breast cells to cytoplasmic and non-apical localization in malignant ductal breast carcinoma." (PMID 25261375, 2014).
enteropathy (2 papers, 2021 to 2025). "Our study demonstrated that CB could ameliorate IND-induced enteropathy by promoting the secretion of MUC2 by goblet cells through inhibiting the Notch signaling pathway." (PMID 40177488, 2025). "The results showed that CB and its secretions may improve IND-induced enteropathy by promoting the secretion of MUC2 via suppressing the Notch signaling pathway." (PMID 40177488, 2025). "The enteropathy was associated with an extensive depletion of goblet cells indicated not only by H&E but also by the more sensitive staining of TFF3, CLCA1, and processed and unprocessed MUC2." (PMID 34237462, 2021).
food allergy (2 papers, 2021 to 2022). Gastrointestinal disturbances, skin eruptions, or shock due to allergic reactions to allergens in food. "IL-33 has been reported to exacerbate food allergy symptoms by increasing degranulation and survival of mast cells, and induce goblet cell differentiation and MUC2 expression." (PMID 36167830, 2022). "In fact, the strong Th2 adjuvant cholera toxin (CT), commonly used to induce food allergy in mouse models, enhances the expression of Cldn2, Muc2, Il17, and Il6 in the small intestine when administered with food proteins to produce sensitization." (PMID 34684302, 2021).
gallbladder carcinoma (2 papers, 2012 to 2020). "The studies on MUC2 expression by gallbladder carcinoma showed that MUC2 expression is related to lower proliferative activity, contrary to MUC1 expression." (PMID 23101681, 2012). "The expression profiles of MUC4, MUC1, MUC2 mucins in gallbladder carcinoma tissues from 63 patients were investigated using immunohistochemical staining." (PMID 23101681, 2012). "For gallbladder carcinoma, positive staining of MUC4, MUC1, and MUC2 was 55.6%, 81.0%, 28.6%, respectively." (PMID 23101681, 2012). "But MUC2 expression has not been related to clinical outcome in gallbladder carcinoma." (PMID 23101681, 2012).
gastric adenoma (2 papers, 2013 to 2021). A neoplastic polyp that arises from the stomach. "For gastric adenoma and tub1/tub2-type GC, more undifferentiated tumors tend to show higher expression of CTSE with MUC5AC and lower expression of MUC2 in tumors, but they tend to present lower expression of CTSE, MUC5AC and MUC2 in background mucosa." (PMID 23451082, 2013). "Intestinal-type gastric adenomas show MUC2 and/or CDX2 expression, whereas the foveolar type is characterized by strong/diffuse MUC5AC positivity, weak/focal MUC6 immunostaining, and an absence of MUC2 or CDX2 expression." (PMID 34206291, 2021).
gastritis (2 papers, 2022 to 2024). Inflammation of the stomach. "Moreover, H. pylori was detected in the gastric juice of some IM patients, which may be related to the abnormal expression of mucin (MUC2) and further develop into IM with gastritis." (PMID 36466659, 2022).
goblet cell adenocarcinoma (2 papers, 2023 to 2024). "Immunohistochemical testing was performed using synaptophysin, chromogranin A, neuronal specific enolase, CD56, CDX-2, CK20, CEA, MUC2 and Ki67, thus establishing the final diagnosis of high-grade extra-appendiceal goblet-cell adenocarcinoma of the cecum, G3." (PMID 40729214, 2024).
hepatocellular carcinoma (2 papers, 2013 to 2017). A malignant tumor that arises from hepatocytes. "Given that the aberrant expression of MUC2, it is conceivable that MUC2 may be also involved in the development of cellular differentiation in Hepatocellular Carcinoma." (PMID 23347460, 2013).
intrahepatic bile-duct carcinoma (2 papers, 2006 to 2013). A cancer that involves the intrahepatic bile duct. "The conventional intrahepatic cholangiocarcinoma (ICC) frequently expressed MUC5AC, but no MUC2, in carcinoma cells." (PMID 23347460, 2013).
invasive carcinoma (2 papers, 2005 to 2020). A carcinoma that is not confined to the epithelium, and has spread to the surrounding stroma. "The pathological findings revealed invasive carcinoma derived from IPNB, and immunohistochemistry revealed positive expression of MUC1, MUC5AC, and MUC6, but negative expression of CDX2 and MUC2." (PMID 33097064, 2020).
metastatic carcinoma (2 papers, 2013 to 2024). A carcinoma which has spread from the original site of growth to another anatomic site. "C5 MUC2+ tumour cells were the least numerous and originated from all tissue types except metastatic tissues, but only accounted for 0.1% in diffuse tissues, indicating that they may not be the product of metastatic cancers." (PMID 38894657, 2024).
periodontitis (2 papers, 2023 to 2025). An acute or chronic inflammatory process that affects the tissues that surround and support the teeth. "To investigate whether FMT can improve intestinal barrier function and reduce inflammation in periodontitis mice, we further analyzed the colonic expression of tight junction proteins, inflammatory cytokines (IL-6, TNF-α), and MUC2 after different treatment conditions." (PMID 41040884, 2025).
Rectal prolapse (2 papers, 2023). Protrusion of the rectal mucous membrane through the anus. "QSOX1 KO mice did not display the growth retardation, occult blood loss, and rectal prolapse exhibited by mice lacking Muc2, the major intestinal gel‐forming mucin." (PMID 36245281, 2023). "MUC2 expression in the colon of Per2−/− mice did not change compared to WT mice, and colon inflammation only occurred when Per2−/− mice developed rectal prolapse." (PMID 37660913, 2023). "The expression of Muc2 and goblet cell differentiation factor Gfi1 in the rectum of Per2−/− mice was also higher than that of WT mice, suggesting that the occurrence of rectal prolapse in Per2−/− mice is not related to impairment of intestinal mucosal immunity." (PMID 37660913, 2023).
squamous carcinoma (2 papers, 2017 to 2024). "However, squamous carcinoma is the predominant type and negative for CK7, CK20, MUC2, and Villin in primary gingival cancer." (PMID 28764790, 2017).
tubular adenoma (2 papers, 2010 to 2017). A usually polypoid neoplasm arising from the glandular epithelium. "Expression of colonic mucins (MUC1, MUC4, MUC17, MUC2, and MUC5AC) and O-glycans [Sialyl LewisA (CA19-9) and Tn/Sialyl-Tn on MUC1] were analyzed in HP (n=33), SSA/P (n=39), and tubular adenoma (TA) (n=36) samples by immunohistochemistry." (PMID 27705923, 2017).
vitamin A deficiency (2 papers, 2015 to 2023). Deficiency of vitamin A due to malnutrition, malabsorption, or dietary lack. "Vitamin A deficiency in rats is associated with an increased abundance of Escherichia coli, decreased mucin-2 (MUC2) and defensin-6, and upregulation of TLR2 and TLR5 expression in the intestine." (PMID 37334221, 2023). "Vitamin A deficiency (control) significantly decreased the mRNA expression levels of MUC2, IgA, EGFR, IL-13 and TGF-β in trachea tissue." (PMID 26422233, 2015).
alcoholic liver diseases (1 paper, 2017). A disorder caused by damage to the liver parenchyma due to alcohol consumption. "Previously, it was proposed that LPS of A. muciniphila is inflammatory in a model of experimental alcoholic liver disease in mice, as the levels of A. muciniphila were higher after chronic intragastric alcohol feeding, and lower in Muc2-/- mice, along with lower plasma LPS concentration." (PMID 28249045, 2017).
ampullary adenocarcinoma (1 paper, 2011). "Expression of MUC1 was high (72%) in ampullary adenocarcinoma, while expressions of MUC2, MUC5AC, and MUC6 were lower." (PMID 22027009, 2011). "For example, normal pancreatic tissue mainly expresses MUC1 and MUC6, while ampullary adenocarcinoma mainly expresses MUC1 and MUC5AC, along with MUC6 and MUC2." (PMID 22027009, 2011). "This study explored the relationships between diagnosis, identification, and survival of ampullary adenocarcinoma and the expressions of MUC1, MUC2, MUC5AC, and MUC6." (PMID 22027009, 2011).
Anxiety (1 paper, 2022). Intense feelings of nervousness, tension, or panic often arise in response to interpersonal stresses. "At the same time, in the marble burying test, Muc2+/+ animals buried fewer marbles consistent with the decreased repetitive behavior and reduced anxiety in mutants." (PMID 36175462, 2022). "Here we show that intestinal microbiota regulates brain glycine and controls anxiety-related and social behaviors in Muc2 knockout mice." (PMID 36175462, 2022). "Muc2 knockout male mice exhibit high exploratory activity, reduced anxiety-related behaviors, impaired sensorimotor gating, and altered social preference towards males and females." (PMID 36175462, 2022). "In the open field test, Muc2+/+ mice showed significantly greater activity in comparison with C57BL/6, and reduced anxiety." (PMID 36175462, 2022). "Our Muc2 model behavioral data unexpectedly demonstrate enhancement of exploratory activity and reduction in anxiety, which is generally not common in chronic intestinal inflammation." (PMID 36175462, 2022).
chronic sinusitis (1 paper, 2015). "MUC2 and MUC5AC expressed in chronic sinusitis mucus behave differently on reduction and proteolytic digestion." (PMID 25691903, 2015).
cystic neoplasm (1 paper, 2024). A benign or malignant neoplasm that contains a single or multiple cystic spaces. "Mucin (MUC) genes, such as MUC1 and MUC2, are associated with different types of pancreatic cysts, with MUC2 typically expressed in IPMNs and MUC1 associated with more aggressive cystic neoplasms." (PMID 39200786, 2024).
depression (1 paper, 2021). "In addition, the abundance of Akkermansia muciniphila was significantly decreased in mice under CRS and UC patients with depression, and positively associated with the expression of MUC2." (PMID 34722332, 2021).
dermatitis (1 paper, 2025). An inflammatory process affecting the skin. "There was a trend toward reduced expression in the OXA group compared to the basal group, suggesting that dermatitis may lead to decreased Muc2 transcription." (PMID 40431255, 2025).
esophagitis (1 paper, 2019). An acute or chronic inflammatory disease affecting the esophageal wall. "Results of immunohistochemistry studies performed to analyze the expression of KLF5, Cdx2, MUC2 and villin in the rat models showed a marked increase in nuclear staining in BE mucosa compared to that in normal esophageal and esophagitis mucosa." (PMID 31632504, 2019). "Similar to human tissue, the rat esophageal tissues showed stepwise increases in the expression of KLF5, Cdx2, MUC2 and villin in the order of normal esophageal, esophagitis and BE squamous epithelium based on immunohistochemical analysis." (PMID 31632504, 2019). "In the assessment of cell lineage distribution, evaluation of the expression of the intestinal markers Cdx2, MUC2 and villin in human BE squamous epithelium revealed increasing expression of Cdx2, MUC2 and villin in the order of normal esophageal, esophagitis and BE tissues." (PMID 31632504, 2019).
esophagus squamous cell carcinoma (1 paper, 2017). "MUC2 shows an interesting role with esophageal histological subtypes, showing a significant 5.5-7.1 fold increase for esophagus adenocarcinoma not otherwise specified (EA NOS) in comparison to esophagus squamous cell carcinoma (ESCA), where the latter showed no significant change." (PMID 28978023, 2017).
gallstones (1 paper, 2022). Solid crystalline precipitates in the biliary tract, usually formed in the gallbladder, resulting in the condition of cholelithiasis. "The increase of MUC1 mucin in the gallbladder epithelium can promote the absorption of cholesterol in mice and inhibit the movement of the gallbladder, thereby promoting the formation of gallstones found MUC1 and MUC2 gene loci significantly associated with gallstones in Chinese males." (PMID 35651949, 2022).
gastric diseases (1 paper, 2013). "As we know, PGC, MUC1, MUC2, the three proteins had solely important diagnostic role for the gastric disease." (PMID 23937908, 2013). "As physiologically functional gastric proteins and “ectopic” expressed protein, the association of PGC, MUC1 and MUC2 solely and gastric diseases had been reported in the past." (PMID 23937908, 2013). "We aimed to investigate the co-expression of PGC, MUC1 and MUC2 which might also give a clue for the understanding of the progression of gastric diseases." (PMID 23937908, 2013). "Phenotypes of PGC, MUC1 and MUC2 co-expression in dynamic gastric diseases are variable." (PMID 23937908, 2013).
Gastric Metaplasia (1 paper, 2023). Intestinal metaplasia of the gastric mucosa is an intermediate precancerous gastric lesion in the gastric cancer cascade from chronic gastritis and atrophy to dysplasia and adenocarcinoma. "To further explore the regulatory effect of this axis on the intestinal epithelial barrier in vivo, we established the conditional knockout mouse model to specifically delete COX in MSCs and found that PGE2 reduction downregulated the gene Muc2 and induced a gastric metaplasia-like phenotype." (PMID 37574502, 2023).
gastric ulcer (1 paper, 2018). An ulcerated lesion in the mucosal surface of the stomach. "As the MUC2 mucin is important in intestinal protection and the MUC6 mucin protects the gastric glands genetic variation could play a role in related diseases such as inflammatory diseases and gastric ulcers." (PMID 30504806, 2018).
gastrointestinal carcinomas (1 paper, 2023). "MUC1, MUC2 and MUC5AC are dominant in MOC and can be used in the differential diagnosis of PMOC and MMOC, particularly in gastrointestinal carcinomas." (PMID 37664708, 2023). "MUC1, MUC2 and MUC5AC are more significant than any other mucins for the differential diagnosis of PMOC and MMOC, particularly in gastrointestinal carcinomas." (PMID 37664708, 2023).
gram-negative bacterial infections (1 paper, 2017). Infections caused by bacteria that show up as pink (negative) when treated by the gram-staining method. "In summary, this study showed that amino acids 1–36 of SAA3 induced MUC2 expression, and we propose a mechanism by which SAA3 induces MUC2 expression in CMT-93 cells after Gram negative bacterial infection." (PMID 28738073, 2017).
H1N1 virus infection (1 paper, 2022). "In the meantime, some downregulated genes (Muc2, Cyp2c55, and Nupr1) and upregulated gene (Slfn4) in response to H1N1 virus infection in mice were verified by Q-RTPCR." (PMID 35677448, 2022).
Helicobacter infection (1 paper, 2017). "In IHC staining, TFF2 and MUC2 were both positive in epithelial cells after chronic Helicobacter infection." (PMID 29212456, 2017).
Hematochezia (1 paper, 2021). The passage of fresh (red) blood per anus, usually in or with stools. "Our results indicated that atractylodin could reduce the weight loss of mice with UC, control diarrhea and hematochezia, alleviate trauma to the colon, reduce the loss of colonic goblet cells, and increase the expression of MUC2, ZO-1, and occludin." (PMID 34335244, 2021).
hepatoid adenocarcinoma (1 paper, 2009). An adenocarcinoma with morphologic characteristics similar to hepatocellular carcinoma, arising from an anatomic site other than the liver. "Four phenotypic categories according to the inmunohistochemical results for CD10, MUC2, MUC5AC, and MUC6 were described for both components, tubular adenocarcinomatous and hepatoid, of hepatoid adenocarcinoma." (PMID 19674468, 2009). "In contrast, no gastric phenotype (MUC5AC+, MUC6+, MUC2-, CD10-) was observed in any of the hepatoid adenocarcinoma components." (PMID 19674468, 2009).
ileal tumors (1 paper, 2021). "Muc2 deficient mice are more prone to ileal infections and develop spontaneous ileal tumors." (PMID 34685068, 2021).
influenza infection (1 paper, 2020). "A recent literature has shown that influenza infection enhanced intestinal Muc2 levels, which may be related to the upregulation of A. muciniphila, due to muc2 is an essential ingredient to maintain the growth of A. muciniphila." (PMID 33603716, 2020).
insomnia (1 paper, 2025). A sleep disorder characterized by difficulty in falling asleep and/or remaining asleep. "Insomnia not only reduces the gut’s antioxidant capacity, anti-inflammatory cytokine levels, mucin 2 (MUC2), and tight junction protein expression but also increases the levels of pro-inflammatory cytokines, leading to intestinal mucosal damage and increased barrier permeability." (PMID 40395724, 2025).
intestinal-type carcinoma (1 paper, 2010). "In a previous study, the CK7+/CK20-/MUC2- pattern in the histological intestinal-type carcinoma and the CK7-/CK20+/MUC2+ pattern in the histological pancreatobiliary-type carcinoma indicated that these different types of ACs had developed from 2 different types of mucosa in the ampulla of Vater." (PMID 21106111, 2010).
intrauterine growth restriction (1 paper, 2022). "Consistent with it, our previous study has found that MFGM promoted the expression of MUC2 and tight junction protein (ZO-1, occuludin, and claudin-1) in intrauterine growth restriction mice." (PMID 35799795, 2022).
iron deficiency (1 paper, 2024). "In this study, iron deficiency and iron overload resulted in downregulation of the tight junction proteins Occludin and Claudin-1 as well as the mucosal proteins MUC1 and MUC2 in jejunum mucosa, which may contribute to a greater susceptibility of neonates to pathogen infection." (PMID 39127747, 2024).
Jaundice (1 paper, 2018). Yellow pigmentation of the skin due to bilirubin, which in turn is the result of increased bilirubin concentration in the bloodstream. "In order to exclude influence from the infection to MUC2 and goblet cells, we chose patients with malignant obstructive jaundice, healthy controls, and patients with malignant tumor without obstructive jaundice." (PMID 29599128, 2018).
Liver abscess (1 paper, 2025). A circumscribed area of pus or necrotic debris in the liver. "Our reanalysis reveals previously unappreciated patterns of Escherichia coli spread during liver abscess formation, clarifies the role of the Muc2 mucin in Listeria monocytogenes systemic spread, and quantifies how Klebsiella pneumoniae replication in the lungs drives systemic dissemination." (PMID 41432445, 2025).